IDH1 (isocitrate dehydrogenase (NADP(+)) 1)
Diseases named in the same sentence as IDH1 in open-access papers (continued):
Sharing a sentence is not in itself a finding about the gene and the disease.
cancer (continued). "Mutant IDH1/2 possess oncogenic properties, and their ectopic expression enhanced cancer cell proliferation, colony formation and inhibits cellular differentiation in vitro." (PMID 28092669, 2017). "Our data reflect the heterogeneity of tumors in the H3/IDH1 wildtype group while also identifying two novel pHGG epigenetic cancer drivers (ZMYND11 and EP300) in this group." (PMID 29084603, 2017). "It would be important to test ACACA inhibitors in other IDH1 mutant cancers and design combination therapies for IDH1 mutant cancers using ACACA inhibitors and mutant-IDH1 inhibitors (such as AG-120)." (PMID 28561042, 2017). "Differences on the importance of IDH1 as compared to IDH2 have been reported for various cancer cell types." (PMID 28806730, 2017). "IDH1 and IDH2 mutations are also responsible for hypermethylation, decreased differentiation, and increased stemness of cancer cells as well as HIF-1α-mediated angiogenesis and growth of tumour." (PMID 28373964, 2017). "Independent of mechanism, our findings highlight another aspect of the unusual metabolic reprogramming of mutant IDH1 cancer cells." (PMID 27144334, 2016). "Mutations of IDH1 and IDH2 have great impact on the development and progression of AML and are attractive targets for cancer treatment." (PMID 27577048, 2016). "The two isoforms, which are mutated in cancer, IDH1 and IDH2, utilize this catalytic process in additional contexts including metabolism and glucose sensing (IDH1) and regulation of oxidative respiration (IDH2)." (PMID 26782057, 2016). "The identification of cancer-associated mutations in the tricarboxylic acid (TCA) cycle enzymes isocitrate dehydrogenases 1 and 2 (IDH1/2) highlights the prevailing notion that aberrant metabolic function can contribute to carcinogenesis." (PMID 27624942, 2016). "The transcription factor EBF1 is an interaction partner of the TET2 gene and is involved in the regulation of DNA methylation in a tissue- and sequence-specific mode of IDH1-mutant cancers." (PMID 27863437, 2016). "With the discovery of isocitrate dehydrogenase (IDH1 and IDH2) mutations in cancer and the associated accumulation of an unique de novo product, 2-hydroxyglutarate (2HG), the phrase ‘oncometabolites’ was coined." (PMID 27635066, 2016). "The mutant IDH1/2 found in human cancer not only have lost their normal catalytic activity but also conferred a neomorphic enzymatic gain-of-function: the NADPH-dependent reduction of α-KG to D-2-hydroxyglutarate (D-2-HG), a trace metabolite in normal cells." (PMID 25825982, 2015). "In cancer, mutant IDH1/2 reduces α-KG to D2-hydroxyglutarate (D2-HG) disrupting α-KG-dependent dioxygenases." (PMID 26178471, 2015). "Our results confirm and expand earlier studies describing how metabolic reprogramming in mutant IDH1 cancer cells translates into changes on the cellular metabolome beyond the overproduction of the oncometabolite 2HG." (PMID 25980580, 2015). "A variety of human cancers, including AML, show recurrent missense mutations in IDH1 and IDH2 that endow the mutant protein with the ability to synthesize 2-hydroxyglutarate (2HG) from αKG." (PMID 25632305, 2015). "NR4A1 also regulates expression of genes such as thioredoxin domain containing 5 (TXNDC5) and isocitrate dehydrogenase 1 (IDH1) to maintain low oxidative stress in cancer cells." (PMID 26035713, 2015). "Nevertheless, neomorphic mutations have recently been demonstrated in isocitrate dehydrogenases 1 and 2 (IDH1 and IDH2), which are mutated in several cancer types such as glioma and AML." (PMID 26024390, 2015). "A second NR4A1-regulated pathway in cancer cells is associated with regulation of genes such as TXNDC5 and IDH1 that maintain high levels of redox equivalents and decrease intracellular stress." (PMID 26035713, 2015).
cancer (continued). "BPTES, an allosteric inhibitor of glutaminase, was found to preferentially slow the growth of cancer cells expressing mutant IDH1 compared with those expressing WT IDH1." (PMID 25980580, 2015). "The recent research of cancer has indicated that the mutant of isocitrate dehydrogenase 1 and 2 (IDH1 and 2) genes will induce various cancers." (PMID 24995286, 2014). "The high NADP+-dependent IDH activity in E478 suggests that the cancer cells compensate the IDH1 defect by upregulating the activity of the mitochondrial IDH2." (PMID 24252742, 2013). "Somatic heterozygous mutations in IDH1 and IDH2 have been recognized recently in a number of cancers." (PMID 23847760, 2013). "Based on this, cancer cells that have heterozygous IDH1 or IDH2 mutations would be expected to contain a mixture of WT:WT, WT:mutant, and mutant:mutant IDH1 or IDH2 dimers." (PMID 21326614, 2011). "We show by coprecipitation that five cancer-derived IDH1 R132 mutants bind IDH1-WT but that three cancer-derived IDH2 R172 mutants exert minimal binding to IDH2-WT." (PMID 21326614, 2011). "IDH1 and IDH2 mutations arise early in cancer pathogenesis and are specific for hotspot codons, suggesting that these mutations have a shared oncogenic function that drives cancer pathogenesis." (PMID 21326614, 2011). "The frequent observation of heterozygous hotspot mutations in IDH1 and IDH2 suggests that they are proto-oncogenes that are activated by these mutations in cancer." (PMID 21326614, 2011). "The fact that the gain of the enzymatic activity to produce 2HG is a shared feature of the IDH1 and IDH2 mutations suggests that this is an important function for these mutants in driving cancer pathogenesis." (PMID 21326614, 2011). "We and others have observed pan-cancer associations between IDH1 mutations, the non-T cell-inflamed TME and immunotherapy resistance." (PMID 41138165, 2025). "D-2-HG is produced by neomorphic activity of mutant IDH1 or IDH2 enzymes in several cancers." (PMID 40931345, 2025). "Given that these PARPi-resistant populations are heterogenous in nature, we sought to probe the effects that specific loss of the end protection factors 53BP1 and REV7 might have on IDH1-mutant cancer cells." (PMID 41357766, 2025). "We recently formally identified IDH1 as a CRC driver gene in an analysis of 100kGP cancers." (PMID 40545636, 2025). "Mutations in isocitrate dehydrogenase 1 (IDH1) and IDH2 not only rewire cellular metabolic pathways but also reshape epigenetic landscapes to promote tumorigenesis, acting as key drivers in various cancers." (PMID 41335282, 2025). "The metabolic gene most commonly found to be altered in cancer is IDH1." (PMID 40956032, 2025). "Significant IDH1 downregulation by G. lucidum may alter cancer cell metabolism by reducing 2-HG production." (PMID 41462671, 2025). "While mutations in IDH1 and IDH2 enzymes, typical producers of 2-HG in certain cancers, are rare in CRC, our findings suggest that a glycolytic phenotype may promote the 2-HG accumulation even without these mutations." (PMID 40185729, 2025). "Our group identified that isocitrate dehydrogenase 1 (IDH1) mutations (mIDH1; R132H and R132C) were associated with a non-T cell-inflamed phenotype across cancers." (PMID 41138165, 2025). "IDH1 and IDH2 mutation-related cancers are increasingly showing abnormal histone and DNA methylation, which may affect stem cell differentiation and ultimately lead to carcinogenesis." (PMID 40017726, 2025). "Ivosidenib is an oral anti-cancer agent that is well-recognized for its ability to target the mutant IDH1 enzyme to reduce the production of the oncometabolite 2-hydroxyglutarate (2-HG), consequently alleviating its oncogenic effects, including epigenetic alteration and metabolism reprograming." (PMID 40299557, 2025). "IDH1 mutations are associated with malignant tumors, disrupt normal metabolic pathways, and lead to abnormal production of carcinogenic metabolites." (PMID 41008893, 2025).
cancer (continued). "IDH1 and IDH2 mutations drive cancer through excessive D-2-hydroxyglutarate (D-2HG) production, disrupting metabolism and epigenetic regulation, and serve as biomarkers for detection and targeted therapy in specific cancers." (PMID 39767571, 2024). "The IDH1 MGPs were predicted to largely affect amino acid-related pathways, in particular glutamate metabolism, which is consistent with the previous studies on this enzyme in cancer cells." (PMID 38468344, 2024). "Oncogenic mutants of isocitrate dehydrogenase 1 and 2 (IDH1/2) induce accumulation of the oncometabolite 2-hydroxyglutarate (2-HG), which impairs HR and generates heterochromatin-dependent DNA replication stress, making IDH1/2 mutant cancer cells hypersensitive to PARPi." (PMID 39007266, 2024). "Therefore, evaluation of IDH1 activity in cancer management is likely to lead to improved modalities." (PMID 38582508, 2024). "For our purposes, it is noteworthy that somatic mutations in IDH1 and IDH2 are found in several cancers – principally acute myelogenous leukemia (AML) and glioblastoma, but also cholangiocarcinomas and chondrosarcomas – and have proven to be effective therapeutic targets." (PMID 39438765, 2024). "In addition, we found IDH1 mutants to be exclusive to LGG in the meRAD51C cases across all cancer types." (PMID 39055334, 2024). "2HG is normally present at low levels but may increase enormously when there are specific mutations in the genes encoding IDH1 or IDH2, and which are associated with several cancers including gliomas, leukemias, and renal cell carcinomas." (PMID 39057706, 2024). "Metabolic screening of tumors could become important, when specific therapies for metabolically dysregulated cancers with SDHx, FH, or IDH1/2 PV become available, as targeted LC-MS/MS analysis is faster and cheaper than sequencing analyses." (PMID 36897220, 2023). "Thus, PCa cells seem more sensitive to wild‐type IDH1 inhibition than in other cancer cell types, possibly due to their specific lineage." (PMID 37086156, 2023). "The survival time of the mice with IDH1-mutant cancer was shorter than in control mice." (PMID 37741882, 2023). "Interestingly, myeloid and glial malignancies also have frequent mutations in IDH1/2, and we have previously linked these mutations to ALT-positive cancers." (PMID 38066546, 2023). "Indeed, one should keep in mind that anti-IDH1 and 2 drugs target a neomorphic, i.e., cancer-specific, activity." (PMID 37561190, 2023). "Notably, in one recent study, FBXW7 deficiency led to defective DNA damage repair and altered metabolic features, which increased NADPH consumption with enhanced sensitivity to radiotherapy in IDH1 mutant cancer cells." (PMID 37176148, 2023). "On the one hand, studies revealing an impact of IDH1 mutation on VTE suggested that this genetic event may drive methylation-mediated down regulation of two procoagulant effectors, TF and PDPN in cancer cells." (PMID 38188342, 2023). "We could demonstrate that mutations observed in MDS cancer cells, including in TET2 and IDH1/2 genes, are also generally observed in NK cells." (PMID 36737440, 2023). "Furthermore, the identification of IDH1 and IDH2 mutations in cancer further emphasizes the direct relationship between metabolic instability and carcinogenesis." (PMID 37569414, 2023). "In last decades, mutations identified in IDH1 and IDH2, and a few other metabolic genes, such as succinate dehydrogenase (SDH) and fumarate hydratase (FH), have provided compelling evidence for metabolic alteration in human cancer development and progression." (PMID 37296846, 2023).
cancer (continued). "Furthermore, isocitrate dehydrogenases 1 and 2 (IDH1/2), which catalyze the conversion of isocitrate to α-ketoglutarate (α-KG), are both abnormally regulated in cancer." (PMID 37176148, 2023). "In addition, survival analyses found that some clinical parameters (cancer type (recurrent patients), WHO grade, 1p19q codeletion, and IDH1-mutation) were the prognosis predictors of LGG patients." (PMID 39280892, 2022). "Intriguingly, we found that NAD+ levels are not altered in IDH1 mutated astrocytes, indicating successful compensatory mechanisms in those cells and, therefore, potentially limiting the vulnerability of cancer cells to NAD+ synthesis inhibition." (PMID 35628596, 2022). "Therefore, inhibitors of mutant IDH1 are counted on to provide a therapeutic benefit in related cancers." (PMID 35402370, 2022). "This phenomenon of isoform switching reinforces the concept that IDH1-mutated cancers are specifically dependent on (R)-2HG rather than on other possible consequences of mutant IDH1 acquisition." (PMID 36056177, 2022). "A spectrum of mutations is observed at IDH1 and IDH2 in cancers." (PMID 35804976, 2022). "This may be due to the production of D-2-hydroxyglutarate (D2HG) via NADPH-dependent reduction of α-KG in IDH1/2-mt cancers." (PMID 36643416, 2022). "Suppression of D-2-HG production by an mtIDH1/2 inhibitor may decrease the BCL2 dependency of IDH1/2mt cancer cells and instead facilitate resistance against venetoclax." (PMID 34967233, 2022). "Therefore, the new highly multiplexed ddPCR is a fast and cost‐effective assay that meets most clinical needs to identify and follow cancer patients in the era of anti‐IDH1/2‐targeted therapies." (PMID 36062346, 2022). "So far only IDH1/2-mutated enzymes have been targeted pharmacologically in cancer, while no direct inhibitors are available for FH, SDH or SUCL loss-of-function malignancies." (PMID 36582801, 2022). "Wild-type IDH1 was identified as a potential therapeutic target in cancer a decade ago." (PMID 35681100, 2022). "Other than the seven previously reported cancer types presenting significant mutations in either IDH1 or SETD2 in the high-methylation group, we found four additional cancer types with small groups of patients whose mutational status significantly correlated with the increased CIMP score." (PMID 35134107, 2022). "Several reports have suggested that IDH1 expression is dysregulated in various cancers." (PMID 35132321, 2022). "In this scenario, Wang and colleagues demonstrated that mutated IDH1 sensitizes cancer cells to erastin-induced ferroptosis, a non-apoptotic form of cell death caused by excessive accumulation of lipid peroxides." (PMID 35740380, 2022). "They additionally showed that IDH1/2 wild-type isoforms prevented the accumulation and overexpression of the hypoxia-inducible factor-1α (HIF-1α), a transcription factor associated with aggressive types of cancer." (PMID 35804976, 2022). "With respect to secondary resistance to mtIDH1/2 inhibitors, several mechanisms have been described, and they may be more universal across the various types of IDH1/2mt cancers." (PMID 34967233, 2022). "However, every single tested allosteric IDH1 inhibitor potently inhibited wtIDH1 activity at lower Mg2+ concentrations in cancer cells." (PMID 35681100, 2022).
cancer (continued). "Notably, 45 (40.18%) patients had the highest-grade carcinomas (WHO grade IV), 51 (45.54%) patients had IDH1 mutations, and 57 (50.89%) patients had recurrence." (PMID 35570844, 2022). "Of note, mutations in IDH1 and IDH2 genes were shown to reprogram the metabolism of cancer cells to produce the onco-metabolite D-2-hydroxyglutarate and cells with mutations might be additionally dependent on lactate (see for review)." (PMID 33800955, 2021). "TCA cycle genes, encoding isocitrate dehydrogenase (IDH1 and IDH2), fumarate hydratase (FH), and succinate dehydrogenase (SDHA, SDHB, SDHC, SDHD, and SDHAF2) are mutated both germinally and somatically in a number of human cancers." (PMID 33572577, 2021). "IDH1 and IDH2 are recurrently mutated in several types of human cancer." (PMID 35996504, 2021). "Our results showed that the IDH1/2 mutations induced altered glucose metabolism, enhanced glucose uptake and glycolysis in MEF cells, which is similar to the Warburg effect acting in cancer cells." (PMID 34516556, 2021). "In addition, FH and IDH mutations lead to tumor initiation through the repression of cellular differentiation, and IDH1 and IDH2 mutations cause an energy shift in cancer cells." (PMID 34445360, 2021). "However, the lack of complete phenotypic overlap between IDH1 mutant and TET2 mutant cancers suggests that IDH1 can modulate leukemogenesis independently of TET2." (PMID 33805247, 2021). "Mutational prevalence of IDH1 and IDH2 genes in various human cancers." (PMID 35996504, 2021). "Therefore, although the contribution of IDH1 mutants to carcinogenic properties has yet to be elucidated, IDH1 mutants have become therapeutic targets for cancer, especially AML." (PMID 33262701, 2020). "Mutation in IDH1 was found to have the strongest association with the non-T cell-inflamed phenotype across all cancers (FDR-adjusted P = 6.75E−16)." (PMID 33106165, 2020). "Indeed, cancer cells in certain metabolic conditions such as hypoxia, rather use glutamine-derived compounds in lipogenesis than the preferential IDH1 pathway resulting compounds." (PMID 32993063, 2020). "In contrast, the formation of its enantiomer d-2-hydroxyglutarate (dr-2HG) is catalyzed by a mutated version of isocitrate dehydrogenase 1 or 2 (IDH1/2) contributing to the pathogenesis of cancer, whereas l-2HG biosynthesis does neither involve IDH1 nor IDH2." (PMID 33585425, 2020). "There is evidence that even major and/or cancer-initiating driver mutations (e.g. APC, IDH1/2, KRAS, PIK3CA, etc.)are differentially selected depending on cancer type, strongly suggesting a role for the TME, broadly defined, in selecting many of the common driver mutations." (PMID 32289242, 2020). "Given that IDH1 resides in peroxisomes, the effect of IDH1 level changes on cancer therapy resistance may be mediated, at least in part, by its function in peroxisomes coupled with NADHP regeneration during ether phospholipid biosynthesis." (PMID 32674458, 2020). "Comparison of isogenic cell lines expressing mutant or wildtype IDH1/2 revealed that cancer cells expressing mutant IDH1/2 exhibited reversible EMT phenotype with a fibroblast-like morphology, along with reduced E-cadherin but increased levels of fibronectin, vimentin and N-cadherin." (PMID 32839493, 2020). "Having established a reference 2-HG HSQC spectrum, we then employed this pulse sequence to acquire the 1H–13C HSQC spectrum of live IDH1-mutant cancer cells (HT-1080) resuspended in phosphate-buffered saline with 10% D2O in a standard 5 mm NMR tube with a 500 MHz NMR." (PMID 32587392, 2020). "On the other hand, IDH1 was found overexpressed in numerous cancers." (PMID 31010244, 2019).